CSF1R (colony stimulating factor 1 receptor)
Diseases named in the same sentence as CSF1R in open-access papers (continued):
Sharing a sentence is not in itself a finding about the gene and the disease.
tumor (continued). "Indeed, small molecule anti-CSF1R drugs are now being tested in several tumour models." (PMID 26066800, 2015). "Indeed, this idea has recently been supported by experimental studies in mouse models for glioblastoma and pancreatic cancer showing that CSF-1/CSF-1R pathway blockade can shift TAM polarization toward an anti-tumor phenotype, resulting in enhanced CD8+ T cell-mediated anti-tumor immunity." (PMID 26500653, 2015). "However, in many tumours CSF-1R and CSFs are also expressed in cancer cells." (PMID 22353646, 2012). "A detailed examination of the Y721F CSF-1R macrophages revealed a significant reduction in motility in vitro and, perhaps more importantly, these macrophages moved less well in vivo and there was a significant reduction in their capacity to enhance tumour cell invasion in vitro." (PMID 22505929, 2012). "M2 TAMs activate the CSF1/CSF1R axis in response to signals such as heat shock protein (HSP)90α secreted by CAFs and tumor cells." (PMID 41426206, 2026). "Studies have shown that blockade of the CSF1/CSF1R pathway reduces the number of M2 TAMs and decreases PD‐L1 and ARG1 expression; it also reshapes the tumor immune microenvironment and enhances sensitivity to immune checkpoint inhibitor therapy." (PMID 41426206, 2026). "They activate the CSF1/CSF1R and IL‐10/STAT3 pathways, induce T‐cell exhaustion and metastatic phenotype switching, promote tumor infiltration and metastasis, and substantially shorten disease‐free and overall survival." (PMID 41426206, 2026). "We set out to conduct a detailed spatial analysis of human CIN3 samples, focusing on the complex interplay between immune cells and the tumour microenvironment, particularly the role of IL34 and CSF1R in tumour progression, as proposed in previous research." (PMID 41362277, 2026). "Surufatinib targets multiple receptor tyrosine kinases involved in tumor angiogenesis and immune modulation, including VEGFRs, FGFR1, and CSF-1R." (PMID 40149728, 2025). "For example, through CSF-1R signaling, TAM-derived CCL8 enhances tumor cell secretion of colony-stimulating factor 1 (CSF-1), a key factor required for the survival and differentiation of macrophages and dendritic cells." (PMID 41584608, 2025). "Recent studies exploring the combination of CSF-1R inhibitors with ICIs and CD40 agonists have shown promise in enhancing anti-tumor immunity." (PMID 40764998, 2025). "CSF1 is secreted by tumor cells and binds to the macrophage-surface CSF1 receptor (CSF1R), which chemotactically converted and polarized macrophages to the M2 phenotype." (PMID 39780291, 2025). "Preclinical models show that CSF-1R inhibition reduces TAM infiltration, disrupts M2 programming, and downregulates the CXCL12/CXCR4 axis, an important pathway for tumor cell survival and chemoresistance." (PMID 41228234, 2025). "Emactuzumab, another monoclonal antibody against CSF1, enhances anti-tumor immune responses by decreasing the number of F4/80+ TAMs within tumors and increasing the CD8+/CD4+ T cell ratio through inhibition of the CSF1/CSF1R-signaling pathway." (PMID 41019045, 2025). "Genetic ablation of CSF1R in murine breast cancer models reduces TAM accumulation and promotes NK cell activation, with adoptive NK cell transfer further enhancing tumour control." (PMID 40948757, 2025). "Studies have shown that co-delivery of CSF-1R inhibitors with cytokine IL-12 or paclitaxel can remodel the immunosuppressive TME, prompt T cell mediated immunity, and effectively suppress tumor growth and metastasis." (PMID 40764998, 2025). "In MMRd tumors, resistance following anti-PD-1 treatment is driven by the expression of TIM3, LAG3, CTLA4, and TIGIT by TILs, as well as tumor clonal selection and the expression of TREM2, CSF1R, IFITM, TMEM176B and IL1B by myeloid cells." (PMID 40027748, 2025).
tumor (continued). "FF-10101, a unique covalently bound inhibitor of CSF1R, reduces immunosuppressive TAMs in the TME and augments antitumor immunity by enhancing tumor-specific CD8+ T cell responses." (PMID 39782686, 2025). "They suggest that tumor-infiltrating M1 (CD86+) and M2 (CSF1-R+) macrophages have a peri-T location and that more macrophages (CD68+) than DLBCL cells (CD20+) express these two markers." (PMID 41415285, 2025). "For example, hypoxic TME promotes tumor cells to secrete several macrophage CSF (MCSF), which binds to the CSF-1 receptor (CSF-1R) expressed on macrophages to recruit and stimulate the polarization of M2 macrophages." (PMID 40033359, 2025). "To investigate the intra-T and peri-T topography and the link of macrophages (CD68+) and tumor B cells (CD20+) with CD86 and CSF1-R expression, we performed IF staining of DLBCL and non-tumor control samples in the same TMAs." (PMID 41415285, 2025). "The CSF receptor inhibitor PLX3397 blocks CSF-1R tyrosine kinase activity and, while it doesn’t reduce TAM infiltration, it shifts TAMs toward the M1 phenotype, inhibiting tumor growth." (PMID 39757310, 2025). "For example, in lung and colon cancers, IL34 sustains tumor growth by promoting cancer cell proliferation and survival through CSF1R activation, whereas in glioblastoma cells, IL34 inhibits tumor proliferation through PTP-ζ activation." (PMID 40538439, 2025). "We synthesise tumour-intrinsic and extrinsic neurotrophic axes, delineate neuro-immune crosstalk, and highlight interventions—TRK/RET inhibitors, CSF1R blockade, β-adrenergic antagonists—aimed at converting this liability into therapeutic leverage." (PMID 41142827, 2025). "To examine the role of tumor cell secreted CSF-1 in regulating macrophage VEGF-A secretion, we first determined if TMEM doorway macrophages express the CSF-1 receptor (CSF-1R)." (PMID 40646332, 2025). "Here, we demonstrated that FF-10101, a high-affinity and covalently bound inhibitor of CSF1R, exhibited a strong and sustained antitumor effect by inducing a tumoricidal M1-like macrophage-rich TME, which led to enhanced tumor-specific CD8+ T cell responses." (PMID 39782686, 2025). "By combining CSF-1R blockage with anti-PD-1 treatment, Peranzoni and colleagues demonstrated that CD8+ T cell tumor infiltration improved, and tumor growth was delayed." (PMID 40422244, 2025). "Due to the high proportion of immunosuppressive macrophages from the tumor mass, antibodies targeting TAM receptors (such as CSF-1R) or the chemokine recruitment system are under development." (PMID 40895574, 2025). "Inhibiting the colony-stimulating factor 1 receptor (CSF1R) can repolarize macrophages towards a pro-inflammatory M1-like phenotype, enhancing anti-tumor immunity and counteracting the tumor-supportive effects of the SASP." (PMID 40750580, 2025). "CD11b is a general myeloid marker, while CCR2, CSF1R, and CD206 are typically expressed in inflammatory monocytes and macrophages, with CD206 serving as a canonical marker of tumor-promoting M2-polarized macrophages." (PMID 40867322, 2025). "Tumor cells may acquire secondary mutations in the target receptor kinases or activate bypass signaling pathways—such as the fibroblast growth factor (FGF) and platelet-derived growth factor (PDGF) axes—that effectively circumvent the inhibitory actions on VEGFR, FGFR, and CSF1R." (PMID 40149728, 2025). "Meanwhile, TAM membranes absorb colony-stimulating factor 1 (CSF1) via increased expression of its receptor (CSF1R) on TAM membranes, reducing TAMs in tumor tissues and relieving TIM." (PMID 40225567, 2025). "Inhibiting the colony-stimulating factor 1 receptor (CSF1R) can effectively deplete M2 macrophages and reprogram them toward a pro-inflammatory phenotype, thereby enhancing anti-tumour immunity." (PMID 40624498, 2025). "We stained the tumor tissue for CD31, TMR-Dextran, and ZO-1 to examine the effects of CSF-1R inhibition on TMEM doorway activity and vascular junctional integrity." (PMID 40646332, 2025).
tumor (continued). "These approaches address challenges like tumor heterogeneity and therapy resistance by combining TAM-targeted strategies (e.g., CSF-1R inhibition, PI3K pathway modulation) with immune checkpoint inhibitors or chemotherapy." (PMID 40422244, 2025). "Blocking CSF-1R signaling by PLX3397 effectively killed TAMs, suppressed GBM development initially, but tumor relapsed rapidly." (PMID 41365876, 2025). "The analysis of the gene signature revealed strong positive correlations with multiple immune checkpoints, including HAVCR2, IL10RA, CSF1R, and CD163, suggesting these genes play a role in regulating the immunosuppressive tumor microenvironment." (PMID 40507280, 2025). "In OSCC, TAMs express receptors such as CD206, CD163, and Toll-like receptors, as well as cytokine and chemokine receptors including IL-1R, CSF-1R, and CCR family members, which serve as biomarkers for TAM quantification and tumor dissemination." (PMID 40948759, 2025). "Targeting the CSF-1/CSF-1R axis has shown potential in reducing GAMM density and altering their phenotype towards a less tumor-supportive state." (PMID 39457693, 2024). "Other novel drugs, including pegylated interleukin 10, colony-stimulating factor 1 receptor inhibitors, CD40 agonists, and C-X-C receptor 4 inhibitors affect the tumor microenvironment and cancer cell metabolism." (PMID 39058879, 2024). "On the other hand, macrophage depletion or a colony stimulating factor 1 receptor (CSF1R) signaling blockade disturb the intratumoral vascular network and reduce food and oxygen delivery to the tumor cells." (PMID 38892209, 2024). "For instance, blocking the colony-stimulating factor 1 receptor (CSF1R) pathway, which is essential for the survival and maintenance of TAMs, has been shown to reduce the population of pro-tumor macrophages and enhance anti-tumor immune responses." (PMID 39769334, 2024). "CSF1R inhibitors play a similar role, and pexidartinib (PLX3397) has been shown to reduce tumor cell proliferation and produce tumor ablation in a variety of cancer models, including gliomas and breast and lung cancers." (PMID 39169402, 2024). "The CSF-1R emerges as a central player in shaping the immune landscape of the TME and targeting this receptor presents promising avenues promoting anti-tumor immunity and potentially improving clinical outcomes in various cancer types." (PMID 39457693, 2024). "Recent discoveries have highlighted the substantial influence of CAFs and the CSF-1/CSF-1R axis on the TME, affecting both tumor progression and immune responses." (PMID 39457693, 2024). "Anti-CSF1R therapy hinders new TAM accumulation, including potential anti-tumor TAM subgroups, while anti-CD40 therapy alters existing TAMs, encompassing functionally distinct TAM subgroups as well." (PMID 38185636, 2024). "Of note, there’s emerging evidence suggesting a synergy between CSF1R signaling and the JAK/STAT3 axis, whereby their coordinated action bolsters the immunosuppressive capacities of MDSCs, further driving tumor immune evasion." (PMID 38992688, 2024). "Macrophages are recruited to tumor sites primarily through the CCL2/CCR2 axis and CSF-1/CSF-1R signaling, so blocking these two signaling axes also reduces macrophage infiltration." (PMID 38464516, 2024). "In agreement with previous reports, the addition of anti-CSF-1R to anti-PD-L1 + anti-TIGIT partially depleted macrophages from the tumour beds of treated mice and sustained tumour responsiveness to checkpoint inhibitors." (PMID 38418879, 2024). "Hence, targeting CSF1R and GM-CSF may facilitate an anti-tumor effect of CAR T cell therapy." (PMID 39835140, 2024). "The binding of CSF-1 to CSF-1R in macrophages can activate PI3K/AKT, Hippo, and Notch signaling pathways, which polarize macrophages to the pro-tumor M2 phenotype." (PMID 38474320, 2024).
tumor (continued). "The colony-stimulating factor 1 receptor (CSF-1R) signaling pathway mainly regulates TAM production, differentiation, and activation, and the detrimental effects of TAM in tumor therapy can be counteracted by CSF-1R inhibitors." (PMID 39678502, 2024). "Accordingly, halting this feedforward loop of TAM recruitment and alternative activation through a combination of CSF-1R and IGF-1R inhibition leads to a further reduction in tumor progression in mice." (PMID 38254796, 2024). "To confirm that macrophages were the critical target of stiripentol in impairing tumor growth and progression, we compared the anti-tumor effect of stiripentol and BLZ945 (an CSF-1R inhibitor that can impair macrophage role in mice) in GL261-bearing mice." (PMID 38443336, 2024). "The efficacy of LNCs@CSF1R siRNA and anti-PD-1, alone and in combination, was evaluated in a murine CRC model with extensive tumor section analyses." (PMID 38992688, 2024). "On the other hand, M-CSF, through its binding with its specific receptor CSF-1R, activates multiple critical downstream signaling pathways such as PI3K/AKT and MAPK/ERK, thereby promoting tumor cell migration." (PMID 38646440, 2024). "Combining CSF1R inhibitors with fibroblast growth factor receptors (FGFRs) offers a promising approach to reducing MDSC infiltration and tumor progression." (PMID 39201328, 2024). "This polarization is driven by CSF-1R signaling, which enhances the secretion of immunosuppressive cytokines such as IL-10 and TGF-β, supporting tumor growth by inhibiting cytotoxic T cell activity and promoting regulatory T cell expansion." (PMID 39796695, 2024). "Collectively, these findings underscore the critical role of CAFs and the CSF-1/CSF-1R axis in tumor progression and immune modulation within the TME and suggest potential therapeutic strategies aimed at enhancing anti-tumor immune responses." (PMID 39457693, 2024). "Activation of MDSCs through CSF1R-mediated pathways strengthens their inhibitory actions on immune effector cells, notably the CD8 + T cells, which are essential for anti-tumor immunity." (PMID 38992688, 2024). "PLX3397, a kinase inhibitor specifically tailored for CSF-1R, synergizes with anti-PD-1 therapy to enhance the infiltration and antitumor activities of CD8+ T cells within tumor tissues." (PMID 38957393, 2024). "Targeting colony-stimulating factor 1 receptor (CSF1R) significantly reduces M2 TAM infiltration and increases CD8 T cell infiltration in CRC tumor tissue, effectively inhibiting tumor growth and metastasis, and improving the response to immunotherapy." (PMID 39262952, 2024). "For HRP tumors, we proposed activating bystander T cells by tumor vaccines or cytokine therapies and targeting M2 macrophages by anti‐CSF1/CSF1R antibodies." (PMID 39136172, 2024). "According to this study, PTK6 expression was positively correlated with CD160, IL10RB, and PVRL2 while being negatively correlated with ADORA2A, BTLA, CSF1R, and KDR in the other tumor types." (PMID 38573548, 2024). "An interesting study conducted on renal carcinoma cells demonstrated how tumor cells can influence the development of CD34+ progenitor cells into mature DCs through the production of IL-6 and CSF-1, which in turn bind to the CSF-1R." (PMID 39457693, 2024). "In a mouse model of CRC orthotopic transplantation, treatment with an inhibitor of the colony-stimulating factor-1 receptor (PLX3397) depleted M2 macrophages and increased CD8-positive T cells infiltrating the tumor nest." (PMID 39000110, 2024). "In the process of CSF1R treatment, not only TAM is significantly inhibited, other immune cells and immune factors in the tumor immune microenvironment are also significantly changed." (PMID 36969873, 2023). "By assessing the elevated expression levels of gene sets corresponding to specific cell type markers, namely PTPRZ1 for tumor cells, MOBP for oligodendrocytes, and CSF1R for macrophages, we successfully classified the cells." (PMID 37662954, 2023).
tumor (continued). "TD-92, an erlotinib derivative targeting CSF1R, not only depletes TAM at the tumor site but also increases the efficacy of anti-PD1 therapy." (PMID 38035101, 2023). "CSF1R inhibitor BZL94540 and TREM‐1 inhibitor GF920 facilitate anti‐tumor curative effect of anti‐PD‐L1 in HCC as well." (PMID 38098217, 2023). "CSF1R, FGFR1, FLT3, and KDR are related to the tumor microenvironment, and ERBB4, STK11, PTEN, and NPM1 are related to proliferation-related factors." (PMID 36780540, 2023). "Patents are pending for CXCR6 transduced T cells for targeted tumor therapy, Improving adoptive cellular therapy, CCR8 transduced T cells for targeted tumor therapy and CSF1R-targeted immunotherapies." (PMID 37534876, 2023). "In preclinical tumor models, improved effects were observed when CSF1/CSF-1R blockade was combined with irradiation, paclitaxel, anti-VEGFR antibody, and ICB." (PMID 37415162, 2023). "Expectedly, the co‐delivery of CSF1R inhibitor and MAPK inhibitor resulted in re‐polarizing M2‐type macrophages to an anti‐tumor M1 phenotype and more robust tumor suppression than single delivery in an aggressive 4T1 tumor model." (PMID 36794651, 2023). "Here, the combination of neoepitope vaccine with anti-CSF1R resulted in a synergistic increased tumor infiltration of CD8 T cells accompanied by epitope spreading and decreased tumor growth." (PMID 37505292, 2023). "Tumor samples were stained for CD68+, CD163+, and CD206+, and CSF1R expression was used to determine the phenotypic expression of cells present in the tumor." (PMID 36769180, 2023). "Regorafenib is an oral multi-kinase inhibitor that targets signaling pathways involved in tumor angiogenesis (VEGFR1-3 and TIE2), oncogenesis (KIT, RET, RAF1, and BRAF), and the tumor microenvironment (PDGFR, FGFR, and CSF1R)." (PMID 37869085, 2023). "The overexpression of stanniocalcin-1 (STC1) in tumor cells inhibits the expression of monocyte chemokine receptors chemokine CCR2, CCR4, and colony-stimulating factor 1 receptor (CSF1R), thereby suppressing the recruitment of monocytes to the TME." (PMID 37663266, 2023). "The TGF-β trap component of CSF1R/CCR2/TGF-β Ab can neutralize TGF-β, thereby enhancing the efficacy of CD8 T cells or NK cells and reducing tumor size in mice." (PMID 38076998, 2023). "The PLX3397 activates the immune response by inhibiting the CSF1/CSF1R pathway in TAMs, further enhancing CD8+ T cell infiltration and reversing tumor immunosuppression (macrophage polarization)." (PMID 36903458, 2023). "The detection of colony-stimulating factor 1 receptor (CSF1R) expression in tumours has also garnered modest excitement; CSFR1 signalling has documented tumour-promoting effects." (PMID 37232837, 2023). "Regorafenib potently blocks several protein kinases that are involved in tumor angiogenesis (VEGFRs 1–3), oncogenesis (BRAF, RAF, RET, KIT), metastasis (FGFR, PDGFR, VEGFR3) and tumor microenvironment (TME) signaling (Tie2, CSF1R)." (PMID 37620408, 2023). "Ongoing clinical trials that target macrophages receptor, CSF-1R, and CCL2–CCR2 signaling axis show promising ablation of tumor-infiltrating macrophages in advanced solid tumors." (PMID 37124547, 2023). "Results according to mouse models of colon cancer revealed that CSF-1R kinase inhibitor PLX3397 combined with anti-PD-1 antibody and oncolytic viruses synergistically conferred significant tumor control and prolonged the survival." (PMID 37386520, 2023). "In the MC38 CRC murine model, selective inhibition of CSF1R reduces the number of CD163+ macrophages and increases the number of cytotoxic CD8+ T-cells within the tumor, thereby delaying tumor growth." (PMID 36765929, 2023). "The first group of studies revealed that the inhibition of the (CSF-1)/CSF-1R pathway, which triggers TAM recruitment into tumor and M2-polarization of the recruits, only pushes the TAMs to the M1-like phenotype, which also causes CD8+ Tc cell activation." (PMID 36902456, 2023).